BCL10 (BCL10 immune signaling adaptor)
Description:
Plays a key role in both adaptive and innate immune signaling by bridging CARD domain-containing proteins to immune activation. Acts by channeling adaptive and innate immune signaling downstream of CARD domain-containing proteins CARD9, CARD11 and CARD14 to activate NF-kappa-B and MAP kinase p38 (MAPK11, MAPK12, MAPK13 and/or MAPK14) pathways which stimulate expression of genes encoding pro-inflammatory cytokines and chemokines. Recruited by activated CARD domain-containing proteins: homooligomerized CARD domain-containing proteins form a nucleating helical template that recruits BCL10 via CARD-CARD interaction, thereby promoting polymerization of BCL10, subsequent recruitment of MALT1 and formation of a CBM complex. This leads to activation of NF-kappa-B and MAP kinase p38 (MAPK11, MAPK12, MAPK13 and/or MAPK14) pathways which stimulate expression of genes encoding pro-inflammatory cytokines and chemokines. Activated by CARD9 downstream of C-type lectin receptors; CARD9-mediated signals are essential for antifungal immunity. Activated by CARD11 downstream of T-cell receptor (TCR) and B-cell receptor (BCR). Promotes apoptosis, pro-caspase-9 maturation and activation of NF-kappa-B via NIK and IKK.
Synonyms: CIPER; c-E10; mE10; CLAP; CARMEN; IMD37
Tractability: PROTAC: UniProt records ubiquitination sites on it; ubiquitination databases record sites on it; its protein half-life has been measured.
Gene: Protein-coding gene on chromosome 1 (85,265,776 to 85,276,632, reverse strand). Ensembl gene ENSG00000142867.
Subcellular location: Cytoplasm, perinuclear region; Membrane raft
Subcellular location (Human Protein Atlas): Cytosol; Nucleoplasm
Pathways (Reactome):
Immune System: Activation of NF-kappaB in B cells; CLEC7A (Dectin-1) signaling; Downstream TCR signaling; FCERI mediated NF-kB activation
Metabolism of proteins: E3 ubiquitin ligases ubiquitinate target proteins
Gene Ontology:
Molecular function: general transcription initiation factor binding; identical protein binding; kinase activator activity; NF-kappaB binding; protease binding; protein binding; protein kinase B binding; protein-macromolecule adaptor activity; transcription coactivator activity; ubiquitin protein ligase binding; CARD domain binding; protein-containing complex binding; signaling adaptor activity
Biological process: adaptive immune response; apoptotic signaling pathway; cellular response to lipopolysaccharide; cellular response to mechanical stimulus; innate immune response; lipopolysaccharide-mediated signaling pathway; negative regulation of mature B cell apoptotic process; positive regulation of apoptotic process; positive regulation of canonical NF-kappaB signal transduction; positive regulation of DNA-templated transcription; positive regulation of extrinsic apoptotic signaling pathway; positive regulation of interleukin-8 production; positive regulation of protein ubiquitination; positive regulation of T cell receptor signaling pathway; programmed cell death; protein homooligomerization; response to food; T cell receptor signaling pathway; toll-like receptor signaling pathway; antifungal innate immune response; neural tube closure; positive regulation of interleukin-6 production; positive regulation of lymphotoxin A production; positive regulation of mast cell cytokine production; regulation of canonical NF-kappaB signal transduction; and 5 more
Cellular component: CBM complex; cytoplasm; cytoplasmic microtubule; cytosol; lysosome; membrane raft; nucleus; perinuclear region of cytoplasm; protein-containing complex; immunological synapse; polkadots
Genetic constraint (gnomAD): Loss-of-function variants: 7 observed, 20.64 expected, observed/expected ratio (o/e) 0.34, 90% interval 0.19 to 0.64. The upper end of that interval is the gene's LOEUF score, 0.64, which puts it in group 2 of 6, group 1 being the genes least tolerant of losing a copy. Missense variants: 196 observed, 280.58 expected, observed/expected ratio (o/e) 0.7, 90% interval 0.62 to 0.79. Synonymous variants: 109 observed, 102.51 expected, observed/expected ratio (o/e) 1.06, 90% interval 0.91 to 1.25.
Gene-disease validity (ClinGen):
ClinGen rates the evidence that BCL10 causes each of these diseases.
immunodeficiency 37 (autosomal recessive): Definitive. Any primary immunodeficiency disease in which the cause of the disease is a mutation in the BCL10 gene.
Cancer hallmarks: escaping programmed cell death (promotes); proliferative signalling (promotes); genome instability and mutations (suppresses); invasion and metastasis (promotes); escaping programmed cell death (suppresses)
Homologues: Orthologues: chimpanzee BCL10 (100% identical), macaque BCL10 (99% identical), rabbit BCL10 (95% identical), dog BCL10 (94% identical), pig BCL10 (93% identical), guinea pig BCL10 (92% identical), rat Bcl10 (91% identical), mouse Bcl10 (91% identical), tropical clawed frog bcl10 (38% identical).
Diseases named in the same sentence as BCL10 in open-access papers:
BCL10 is named in the same sentence as 101 diseases in open-access papers, as found by Europe PMC text mining. Sharing a sentence is not in itself a finding about the gene and the disease. The quoted sentences say what the papers report.
MALT lymphoma (31 papers, 2006 to 2023). An indolent, extranodal type of non-Hodgkin lymphoma composed of small B-lymphocytes (centrocyte-like cells). "BCL10 (B-cell CLL/lymphoma 10) is involved in a translocation found in B-cell lymphomas of mucosa-associated lymphoid tissue (MALT lymphomas)." (PMID 22429919, 2012). "Further, MALT1-dependent cleavage of BCL10 reportedly controls integrin-dependent adhesion of T cells and MALT lymphomas." (PMID 36719376, 2023). "Overexpression of Bcl10 is an indicator of constitutive NF-κB activation in tumors including MALT lymphoma, and persistent NF-κB activation is known to characterize severe uncontrolled asthma." (PMID 35885021, 2022). "Just as in the case of MALT lymphoma, high Bcl10 expression in fibrotic airway tissues is paradoxical, considering that Bcl10 is a pro-apoptotic CARD-containing adaptor molecule." (PMID 35885021, 2022). "Chromosomal translocations associated with MALT lymphoma include API2/MALT1, IGH/MALT1, BCL10/IGH, and trisomy 3 and 1814,23,27." (PMID 34873224, 2021). "In contrast to hematological malignancies, such as MALT lymphoma, BCL10 was rarely found in the nucleus of solid tumors." (PMID 34412631, 2021). "Intriguingly, BCL10 protein is aberrantly expressed in the nuclei of lymphoma cells, suggesting an as-of-yet unappreciated role of nuclear BCL10 in the pathogenesis of MALT lymphoma." (PMID 28561798, 2017). "Initially immunohistochemical evaluation of Bcl10 has been proposed as a good surrogate marker of translocations in MALT lymphomas." (PMID 22472082, 2012). "The important function of MALT1 and BCL10 in antigen receptor signalling to NF-κB suggests a role for enhanced NF-κB activation in MALT lymphoma development." (PMID 19279678, 2009). "As MALT1-API2 is very unstable being an efficient target of its own E3 ubiquitin ligase activity, this suggests that its protein level in MALT lymphoma might be too low to affect BCL10 stability and localization." (PMID 19279678, 2009). "As we observed MALT1-API2 to be an efficient target of its own E3 ubiquitin ligase activity, our data suggest that this inherent instability of MALT1-API2 prevents its accumulation and renders a potential effect on MALT lymphoma development via destabilization of BCL10 unlikely." (PMID 19279678, 2009). "Up to 50% of MALT lymphomas carry a chromosomal translocation resulting in the production of a chimeric protein (BIRC3-MALT1) and in transcriptional deregulation of BCL10, MALT1, and FOXP1, with variable frequencies depending on the site of occurrence." (PMID 33499258, 2021). "Chromosomal translocations involving the genes BCL10 or MALT1, which are frequent in other types of MALT lymphomas, are rare in OAML." (PMID 27566587, 2016). "In conclusion, these data do not suggest an effect of MALT1-API2 expression on BCL10 protein levels and nuclear staining in these MALT lymphomas." (PMID 19279678, 2009). "In addition, BCL10 interacts with the MALT1 paracaspase (also known as PCASP1), which was initially discovered from a chromosomal translocation leading to the expression of the oncogenic API2-MALT1 fusion protein in MALT lymphoma." (PMID 30022982, 2018). "However, the expression of MALT1-API2 did not affect the nuclear staining of BCL10 in our MALT lymphoma cases analyzed." (PMID 19279678, 2009). "The absence of translocations affecting the genes BCL10, MALT1, BIRC3, or FOXP1, as they are frequently seen in other types of MALT lymphomas, in six OAML analyzed by WGS is in line with published data." (PMID 32316399, 2020). "In MALT lymphomas arising at gastrointestinal locations, it is claimed that MALT1, with or without bcl10 cooperation, activates the phosphorylation cascade, leading to IkB-α phosphorylation." (PMID 22472082, 2012). "However, two different transgenic mice—overexpressing either of the two translocations, BCL10 or BIRC2-MALT1, seen frequently in MALT lymphomas—develop splenic marginal zone hyperplasia, but not lymphoma." (PMID 25922601, 2015).
lymphoma (19 papers, 2009 to 2025). A malignant (clonal) proliferation of B- lymphocytes or T- lymphocytes which involves the lymph nodes, bone marrow and/or extranodal sites. "One of the functions of BCL10 protein is to activate NF-κB, thereby promoting cell growth, and its aberrant expression is associated with the occurrence and development of lymphoma." (PMID 39469643, 2024). "B-cell lymphoma/leukemia 10 (BCL10), a protein whose mutation is implicated in certain types of lymphoma, is phosphorylated at multiple sites by IKKβ and consequently degraded." (PMID 29292732, 2017). "Venetoclax plus pirtobrutinib synergized in overcoming resistance and potently killed BCL10-mutant lymphomas in vitro and in vivo." (PMID 39894894, 2025). "We previously demonstrated that nuclear BCL10 translocation participates in the instigation of NF-κB in breast cancer and lymphoma cell lines." (PMID 34412631, 2021). "Chromosome 18 includes the gene MALT1, which encodes a caspase-like protease that plays a role in BCL10-induced activation of the NF-κB pathway and thus, the overexpression of MALT1 as seen in trisomy 18 has been associated with lymphoma progression." (PMID 33804823, 2021). "Here, we develop novel BCL10 peptide inhibitors (BPIs) that not only can inhibit intracellular BCL10 polymerization but can also destabilize the BCL10 protein in lymphoma cells." (PMID 33052237, 2020). "Taken together, BCL10 acts as a platform that integrates many components of the ubiquitin system, which control BCL10 activity and stability in lymphocytes and lymphoma cells." (PMID 30022982, 2018). "Using the top-scoring pairs method, the expression differential between CAV1 and BCL10 identified lymphoma samples with 98.4% sensitivity and 88.5% specificity." (PMID 26566034, 2015). "First, small-molecule inhibitors disrupting the CBM complex could abrogate BCL10 signaling, with precedent from MI-2 in lymphoma models." (PMID 40539049, 2025). "Bcl10, specifically filamentous Bcl10, is required for the survival of ABC-DLBCL cells and other types of lymphoma cells 54, suggesting it as an attractive target for therapeutic intervention." (PMID 33052237, 2020). "The CD19 negative DLBCL were characterized further for other B cell lineage and lymphoma markers including CD20, PAX5, CD138, BCL2, BCL6, BCL10 and MUM1 using immunohistochemistry." (PMID 28484276, 2017). "In addition, the lymphoma cells carrying IGH/MALT1 show not only over-expression of MALT1, but also BCL10 accumulation in cytoplasm." (PMID 35008340, 2021). "Consequently, cell lines derived from such lymphomas, such as HBL-1 and OCI-Ly3, show a constitutive presence of cleaved BCL10 that can be detected with an antibody specifically recognizing the processed form of this protein." (PMID 25105596, 2014). "Seventy-two cases were stained for BCL10 and MUM1: all CD19 negative lymphoma, and 56/78 CD19 positive lymphoma." (PMID 28484276, 2017). "The different frequencies of BCL10 and MUM1 positive cases were not significant between CD19 negative and positive lymphoma." (PMID 28484276, 2017).
B-cell lymphomas (12 papers, 2012 to 2025). "B-cell lymphoma/leukemia 10 (Bcl10) is an adaptor protein associated with the constitutive activation of canonical NF-κB in mucosa-associated lymphoid tissue (MALT) B cell lymphoma." (PMID 35885021, 2022). "CARD9 is an upstream activator of BCL10 and NF-kappaB signaling, which is important to B cell lymphomas of mucosa-associated lymphoid tissue." (PMID 30723747, 2019). "BCL10 plays an important role in the development of B‐cell lymphomas of mucosa‐associated lymphoid tissues." (PMID 28158919, 2017). "In addition, Aberrant CBM function resulting from BCL10 mutations is a key factor in a range of diseases, including B-cell lymphoma, autoimmune diseases, and IBD." (PMID 38289597, 2024). "Examination of alterations in key pathways implicated in B-cell lymphomas suggests involvement in chromatin remodelling (CREBBP and EP300) and regulators of NF-κB signalling (TNFAIP3, BCL10, MYD88, CD79B and CARD11) were affected." (PMID 39460552, 2024). "Besides, acinar markers were also frequently positive, with Trypsin showing the most prominent expression in 31cases (45.59%), followed by Chymotrypsin and BCL‐10 (B‐Cell Lymphoma/Leukemia 10)." (PMID 39162366, 2024).
diffuse large B-cell lymphoma (7 papers, 2017 to 2025). "CK1α is a tumor supporter in diffuse large B cell lymphoma (DLBCL) of activated B cell subtype, inducing the activation of NF-κB through the regulation of the CBM1 complex (CARD11, BCL10, MALT1)." (PMID 28969692, 2017). "Furthermore, in diffuse large B-cell lymphoma (DLBCL) and mantle cell lymphoma (MCL), CK1α contributes to the constitutive activation of the NFκB pathway along with the CARD11/BCL10/MALT1 (CBM) complex." (PMID 38265263, 2024). "The aggressive activated B-cell like (ABC) subtype of diffuse large B-cell lymphoma (DLBCL) exploits a multi-protein complex of CARMA1, BCL10, and MALT1 (CBM complex), which normally conveys NF-κB signaling upon antigen receptors engagement." (PMID 30474008, 2018).
pancreatic cancer (7 papers, 2013 to 2025). "Immunohistochemistry was positive for trypsin and BCL-10, indicating that the pancreatic tumour was ACC." (PMID 35462149, 2022). "Immunohistochemistry was positive for trypsin and BCL-10, indicating the pancreatic tumour to be ACC." (PMID 35462149, 2022). "In this study, we demonstrated that BCL10 inhibition can result in differential cell cycle arrest in the two different pancreatic cancer cell lines: mutant KRAS cell lines (G2/M arrest) and wild-type KRAS cell lines (G1 arrest)." (PMID 34412631, 2021). "Second, shRNA nanoparticles targeting BCL10 mRNA may achieve selective knockdown while minimizing systemic effects, as demonstrated in pancreatic cancer." (PMID 40539049, 2025). "To investigate whether BCL10-mediated suppression of proliferation of pancreatic cancer cells is via the cell cycle arrest, we assessed the effects of shBCL10 transfection on cell cycle regulation in three PDAC cell lines." (PMID 34412631, 2021). "Interestingly, DNA-chip hybridization assays identified both BCL-6 and BCL-10 as novel candidate genes in pancreatic cancer that were overexpressed in pancreatic cancer cell lines and primary tumor samples." (PMID 23737761, 2013). "Reliable markers of PACC have been slowly emerging such as carcinoembryonic antigen (CEA), cytokeratin 18 (CK18) and B-cell lymphoma/leukemia 10 (BCL10) allowing us to distinguish acinar cell carcinoma from normal acinar cells or other pancreatic cancers through histology." (PMID 27165126, 2016).
breast carcinoma (5 papers, 2018 to 2021). "Indeed, we found that that AGTR1 overexpression, in both breast cancer patient samples and breast cancer cell lines, drives NF-κB activation and an associated NF-κB gene expression signature; as we expected, CARMA3, Bcl10, and MALT1 are each required for this to occur." (PMID 30158935, 2018). "Aberrant CARMA3/BCL10/MALT1 has been indicated in several cancers, including ovarian cancer, breast cancer, and prostate cancer 59-61." (PMID 33052237, 2020). "The drug was also able to significantly increase the nuclear condensation, and modulated the expression of certain genes involved in breast cancer, such as caspases 3, and 9, BAK-1, C-MYC, BCL2L1, BCL-10, and BCL-2." (PMID 32746451, 2020). "Aripiprazole also increased the expression of certain pro-apoptotic genes (caspases 3, and BCL10), while expression of anti-apoptotic genes (BCL2L1, and c-myc) that are involved in the progression of breast cancer were decreased." (PMID 32746451, 2020). "In consideration of our validated targets, Tollip and Bcl10, the role of Tollip in breast cancer has not been extensively explored, making our present study highly novel." (PMID 33322811, 2020). "Furthermore, using a mouse model of AGTR1 + breast cancer, we found that suppression of C3BM signaling using an shRNA directed against Bcl10 results in significantly impaired tumor angiogenesis." (PMID 30158935, 2018).
Immunodeficiency (5 papers, 2018 to 2022). Failure of the immune system to protect the body adequately from infection, due to the absence or insufficiency of some component process or substance. "Moving beyond infections, both MALT1- and BCL10-deficient patients presented simultaneously with immunodeficiency and immune dysregulation, where in addition to recurrent infections, they also developed inflammatory gastrointestinal disease." (PMID 30283440, 2018). "The autosomal–recessive BCL10 deficiency in humans caused combined immunodeficiency that largely mirrored the phenotype of BCL10−/− mice with respect to lymphocyte signaling and activation." (PMID 30022982, 2018). "This study also identified immune disease-related genes associated with somatic mutations such as MYD88 and BCL10 in NF-κB signaling, CD79B, PAX5, and BCR in B-cell development, and MYH11, RUNX1, and TET2 in leukemia." (PMID 29937999, 2018). "T and B lymphocytes from BCL10-deficient mice are defective in NF-κB signaling, fail to upregulate cytokines like IL-2, and do not proliferate in response to TCR and BCR stimulation, which leads to blunted antigen responses and severe immune deficiency." (PMID 30022982, 2018).